CLASP1 (cytoplasmic linker associated protein 1)
Description:
Microtubule plus-end tracking protein that promotes the stabilization of dynamic microtubules. Involved in the nucleation of noncentrosomal microtubules originating from the trans-Golgi network (TGN). Required for the polarization of the cytoplasmic microtubule arrays in migrating cells towards the leading edge of the cell. May act at the cell cortex to enhance the frequency of rescue of depolymerizing microtubules by attaching their plus-ends to cortical platforms composed of ERC1 and PHLDB2. This cortical microtubule stabilizing activity is regulated at least in part by phosphatidylinositol 3-kinase signaling. Also performs a similar stabilizing function at the kinetochore which is essential for the bipolar alignment of chromosomes on the mitotic spindle.
Synonyms: KIAA0622; MAST1
Tractability: PROTAC: ubiquitination databases record sites on it; its protein half-life has been measured.
Gene: Protein-coding gene on chromosome 2 (121,337,776 to 121,649,599, reverse strand). Ensembl gene ENSG00000074054.
Subcellular location: Cytoplasm, cytoskeleton; Cytoplasm, cytoskeleton, microtubule organizing center, centrosome; Chromosome, centromere, kinetochore; Cytoplasm, cytoskeleton, spindle; Golgi apparatus, trans-Golgi network
Pathways (Reactome):
Cell Cycle: AURKA Activation by TPX2; Amplification of signal from unattached kinetochores via a MAD2 inhibitory signal; EML4 and NUDC in mitotic spindle formation; Loss of Nlp from mitotic centrosomes; Loss of proteins required for interphase microtubule organization from the centrosome; Mitotic Prometaphase; Recruitment of NuMA to mitotic centrosomes; Recruitment of mitotic centrosome proteins and complexes; Regulation of PLK1 Activity at G2/M Transition; Resolution of Sister Chromatid Cohesion; Separation of Sister Chromatids
Developmental Biology: Role of ABL in ROBO-SLIT signaling
Organelle biogenesis and maintenance: Anchoring of the basal body to the plasma membrane
Signal Transduction: RHO GTPases Activate Formins
Gene Ontology:
Molecular function: dystroglycan binding; kinetochore binding; microtubule binding; microtubule plus-end binding; protein binding; tubulin binding
Biological process: astral microtubule organization; basement membrane organization; cell division; establishment of mitotic spindle localization; establishment of spindle orientation; exit from mitosis; Golgi organization; microtubule anchoring; microtubule bundle formation; microtubule cytoskeleton organization; microtubule nucleation; microtubule organizing center organization; mitotic spindle organization; negative regulation of microtubule depolymerization; negative regulation of microtubule polymerization or depolymerization; negative regulation of stress fiber assembly; negative regulation of wound healing, spreading of epidermal cells; positive regulation of epithelial cell migration; positive regulation of exocytosis; positive regulation of extracellular matrix disassembly; regulation of focal adhesion assembly; vesicle-mediated transport; establishment or maintenance of cell polarity; mitotic spindle assembly; positive regulation of microtubule polymerization; and 1 more
Cellular component: basal cortex; cell cortex; centrosomal corona; centrosome; cortical microtubule cytoskeleton; cytoplasmic microtubule; focal adhesion; Golgi apparatus; kinetochore; membrane; spindle microtubule; cytosol; kinetochore microtubule; microtubule associated complex; microtubule organizing center; microtubule plus-end; mitotic spindle; cytoskeleton; spindle
Genetic constraint (gnomAD): Loss-of-function variants: 20 observed, 122.68 expected, observed/expected ratio (o/e) 0.16, 90% interval 0.11 to 0.24. The upper end of that interval is the gene's LOEUF score, 0.24, which puts it in group 1 of 6, group 1 being the genes least tolerant of losing a copy. Missense variants: 1,183 observed, 1,559.4 expected, observed/expected ratio (o/e) 0.76, 90% interval 0.72 to 0.8. Synonymous variants: 586 observed, 596.57 expected, observed/expected ratio (o/e) 0.98, 90% interval 0.92 to 1.05.
Homologues: Orthologues: macaque CLASP1 (98% identical), chimpanzee CLASP1 (97% identical), rat Clasp1 (97% identical), mouse Clasp1 (97% identical), pig CLASP1 (96% identical), dog CLASP1 (96% identical), rabbit CLASP1 (92% identical), guinea pig CLASP1 (92% identical), tropical clawed frog clasp1 (79% identical). Paralogues in human: CLASP2 (68% identical), TOGARAM1 (15% identical), TOGARAM2 (11% identical).
Diseases named in the same sentence as CLASP1 in open-access papers:
CLASP1 is named in the same sentence as 19 diseases in open-access papers, as found by Europe PMC text mining. Sharing a sentence is not in itself a finding about the gene and the disease. The quoted sentences say what the papers report.
ovarian carcinoma (2 papers, 2014 to 2015). A malignant neoplasm originating from the surface ovarian epithelium. "Thus, four genes that were validated in respect to OS (MBNL1, SPPLB2, VAV2, and CLASP1) were further tested in the independent set of 30 ovarian cancer samples." (PMID 24478986, 2014).
autism (1 paper, 2022). Persistent deficits in social interaction and communication and interaction as well as a markedly restricted repertoire of activity and interest as well as repetitive patterns of behavior. "SHANK1 and CLASP1 were co-identified in three types of DEPs, which may perform a key function in the pathogenic mechanism of autism and the therapeutic effect of DBS." (PMID 36474209, 2022).
congenital nystagmus (1 paper, 2025). Nystagmus present at birth or caused by lesions sustained in utero or at the time of birth. "The window of ±500 kb from the significant SNP also included the gene CLASP1, for which mutations have been related to disorders, such as epiphyseal dysplasia that affect cartilage and bone development, especially in the long bones in the limbs, short stature, microcephaly and congenital nystagmus." (PMID 39754479, 2025).
diabetes (1 paper, 2023). "We discovered by data analysis and review of the literature that Dgkh, Clasp1, and Pde1b are linked to central nervous system disease; however, only Dgkh showed reduced levels in the case of diabetes and HG-treated HN-h cells." (PMID 37385994, 2023).
melanoma (1 paper, 2025). A malignant, usually aggressive tumor composed of atypical, neoplastic melanocytes. "For example, the paralog pair CLASP1/CLASP2 displayed a much stronger genetic interaction effect in lung and pancreatic models than in melanoma models (P = 0.0001, FDR: 0.011)." (PMID 40968372, 2025).
Myotonia (1 paper, 2018). An involuntary and painless delay in the relaxation of skeletal muscle following contraction or electrical stimulation. "In DM1 and DM2 individuals without clinical myotonia, splicing of MBNL2, MBNL1, CLASP1, and MAP3K4 showed changes intermediate between those with myotonia and UA subjects." (PMID 30254196, 2018).
neuroblastoma (1 paper, 2019). Neuroblastoma (NB) is the most common solid, extracranial childhood tumor. "Here, we show that in differentiating N1E-115 neuroblastoma cells CLASP1 and CLASP2 differ in their accumulation at MT plus-ends and display different sensitivity to GSK3-mediated phosphorylation, and hence regulation." (PMID 30787869, 2019). "We have studied the functions of CLASP1 and -2 in differentiating N1E-115 neuroblastoma cells, and in Clasp2 mouse knockout (KO) neurons." (PMID 30787869, 2019). "Here, we reveal distinct functions for the CLASPs in N1E-115 neuroblastoma cells with CLASP1 stimulating neurite outgrowth and CLASP2 acting as a break." (PMID 30787869, 2019). "Taken together these data indicate that the localization of CLASP1 and -2 proteins differs during neuronal differentiation, both in neuroblastoma cell lines and in primary neurons." (PMID 30787869, 2019). "To address CLASP1 and CLASP2 function and behavior in neuronal cells, we used the N1E-115 mouse neuroblastoma cell line." (PMID 30787869, 2019). "Moreover, WB analyses also indicated that in neuroblastoma cells CLASP2 is phosphorylated by GSK3 but CLASP1 is not." (PMID 30787869, 2019).
osteonecrosis (1 paper, 2021). A none disease characterized by death of bone tissue due to a lack of blood supply. "In the Steroid-induced osteonecrosis of the femoral head-bone marrow mesenchymal stem cells, five circRNA targeted mRNAs including CLASP1, ENOX2, SYK, UBE2G2, and WNT5B were up-regulated by circRNA42." (PMID 34753940, 2021).
schizophrenia (1 paper, 2021). A major psychotic disorder characterized by abnormalities in the perception or expression of reality. "CLASP1 was a protein from axon guidance down-regulated in schizophrenia and further studied in two murine stress models in this study." (PMID 34576238, 2021).
Theileria infection (1 paper, 2017). "Disruption of CLASP1 function with a dominant negative mutant in Theileria-infected cells caused MT bundling and induced a dramatic alteration in parasite size, morphology, and position, emphasizing how important proper MT dynamics are for Theileria infection." (PMID 28861517, 2017). "To check whether CLASP1 association with the schizont is a general phenomenon associated with Theileria infection, we therefore also analyzed the localization of CLASP1 in a clonal line of T. annulata-infected PBM cells (clone TaD7) and in Theileria parva-infected T cells (Tp_951T_F31)." (PMID 28861517, 2017). "We found CLASP1 to coat the schizont in both cell lines, suggesting that the sequestration of this host cell protein is likely to be a general feature of Theileria infection." (PMID 28861517, 2017).
tumor (3 papers, 2015 to 2025). "CLASP1 is not differentially expressed in tumor versus mucosa in HNSCC." (PMID 40768535, 2025).
cancer (2 papers, 2012 to 2022). A tumor composed of atypical neoplastic, often pleomorphic cells that invade other tissues. "Among genes downregulated by clofibrate, the major part belonged mainly to functional groups: “cancer” (STIP1, HNRNPA1, VIL1, and CDH1) and “cellular assembly and organization” (CLASP1 and MACF1)." (PMID 22619672, 2012).
infection (2 papers, 2017 to 2021). The state of being infected such as from the introduction of a foreign agent such as serum, vaccine, antigenic substance or organism. "Infection with herpes simplex virus 1 (HSV-1) induces the stabilization of MTs in human fibroblasts in a CLASP1-dependent manner." (PMID 28861517, 2017). "Analysis of freshly infected peripheral blood mononuclear (PBM) cells revealed that CLASP1 associates with the sporozoite as early as 30 min postinfection, suggesting that CLASP1 may be involved in the recruitment of MTs to the sporozoite surface during the establishment of infection." (PMID 28861517, 2017). "Using lentivirus-mediated infection, from cells expressing endogenous mCherry-PRC1, we generated cells also stably expressing ectopically EGFP-tagged central spindle protein CLASP1." (PMID 34580180, 2021).
central nervous system disease (1 paper, 2023). "By analyzing our data and reviewing the literature, we found that Dgkh, Clasp1 (cytoplasmic linker-associated protein 1), and Pde1b (phosphodiesterase 1b) are closely related to central nervous system disease." (PMID 37385994, 2023).
CLASP1 also shares sentences with these, for which no sentence is quoted: Alzheimer disease (1 paper); depression (1); Epiphyseal dysplasia (1); head and neck cancer (1); microcephaly (1).